CXCR4 (C-X-C motif chemokine receptor 4)
Diseases named in the same sentence as CXCR4 in open-access papers (continued):
Sharing a sentence is not in itself a finding about the gene and the disease.
tumor (continued). "In this context, we examined the expression pattern of MIF and CXCR4 in different cell populations in tumor tissues from 136 patients with ESCC, to determine the predictive value of the MIF and CXCR4 expressions in different cell populations within tumor microenvironment of ESCC." (PMID 23497377, 2013). "The immunohistochemistry for CD34 was examined on the primary tumor tissue sections to determine whether the suppression of primary tumor growth was a result of an antiangiogenic effect (i.e., the inhibition of microvessel formation) of the CXCR4 antagonist." (PMID 24137439, 2013). "Interestingly, our results showed for the first time that the combined expression of MIF and CXCR4 in tumor cells was also an independent prognostic marker for ESCC patients and was strongly associated with reduced survival." (PMID 23497377, 2013). "In the MIN-O lesions the percentage CXCR4+ and CXCR4++ cells varied during tumor progression." (PMID 23326303, 2013). "Further, inhibition of the interaction of SDF-1α and CXCR4 impairs metastasis of BC cells to regional lymph nodes and lung, suggesting that chemokines and their receptors are involved in determining the metastatic destination of tumor cells." (PMID 25285238, 2013). "In addition to its critical role in tumor cell growth, survival and angiogenesis in multiple cancers, the CXCR4/SDF1 axis has been shown to mediate homing and metastatic secondary growth in SDF1-producing organs, such as liver and bone marrow." (PMID 24376734, 2013). "As a result the in vivo SPECT/CT images obtained in this study provide less of a black and white discrimination between CXCR4 positive tumors and their background, than can be obtained using transfected tumor cells with extremely high levels of CXCR4 expression." (PMID 23326303, 2013). "Additionally, inhibition of CXCR4 with CTCE-9908 resulted in decreased tumor growth, angiogenesis, and lymphangiogenesis, as well as increased apoptosis in a xenograft PC model." (PMID 23902739, 2013). "The effects of SDF-1 are complex as it can influence tumor growth at several levels such as survival and growth of cells, cell adhesion, attraction of endothelial progenitors and CXCR4 expressing fibrocytes, as well as altered angiogenesis and matrix formation." (PMID 23593347, 2013). "The CXCL12/CXCR4 axis is involved in tumor progression, angiogenesis, metastasis, and survival, and promising results in preclinical tumor models indicate that CXCR4 antagonists may have antitumor activity in patients with various malignancies." (PMID 23987636, 2013). "Furthermore, the percentage of strongly CXCR4 positive cells was significantly higher in all stages of MIN-O progression compared to the percentage found in the control 4T1 tumor lesions (44.6±6.0%; p<0.001)." (PMID 23326303, 2013). "In cancer, CXCR4 expression was first correlated with the metastatic capability of breast and melanoma cancer cells; then a direct correlation between receptor upregulation and tumor progression, neovascularization, invasion and metastasis was demonstrated." (PMID 24058588, 2013). "Although only CXCR4 was used in this proof of concept study, this approach can readily be expanded to other targeting hybrid imaging agents and will help increase the clinical applicability of tumor specific imaging approaches." (PMID 23326303, 2013). "CXCR4 is involved in homing of metastatic spread in numerous tumor entities." (PMID 23082154, 2012). "Interestingly, although the limited number of benign and metastatic lesions, but including normal tissues, we observed a statistically significant correlation between CXCR4 score levels and the increase of tumor grade or metastases." (PMID 22417013, 2012). "CXCL12 has multiple roles in tumour pathogenesis by promoting tumour growth, enhancing tumour angiogenesis, suppressing tumour immunity and participating in tumour metastasis via expression of CXCR4." (PMID 22415233, 2012).
tumor (continued). "The combined inhibition of HER2 and CXCR4 leads to further reduction for primary tumor growth." (PMID 23082154, 2012). "And in the other hand, VEGF could up-regulate the expression of CXCR4 in vascular endothelial cell, thus promote the migration of EPCs and contribute to tumor neovascularization." (PMID 22745705, 2012). "CAFs also secrete stromal cell-derived factor 1 (SDF-1), which stimulates tumor growth by activating its receptor, CXCR4, on tumor cells and by functioning as a chemoattractant for the recruitment of bone-marrow-derived endothelial progenitor cells that subsequently promote angiogenesis." (PMID 22174714, 2012). "The binding of CXCL12 to its receptor CXCR4 is thought to induce proliferation of tumour cells." (PMID 22415233, 2012). "The in vitro results suggested that chemotactic CXCL12/CXCR4-signaling is a crucial determinant of site-specific tumour cell extravasation into the liver that was further analysed using the in vivo model for hepatic tumour cell colonization." (PMID 22253872, 2012). "MT1-MMP in coordination with CXCR4 promotes invasion and dissemination of the tumor." (PMID 22242160, 2012). "This indicates that small molecule antagonists against CXCR4 can interfere with tumour progression and metastasis and may potentially be used for new therapeutic inventions." (PMID 22518090, 2012). "Because Neu-YB tumor cells have been shown to express more CXCL12 than the other mutants and Neu-NDL, we investigated whether CXCR4 signaling plays a role in EGF-induced in vivo invasion in that tumor." (PMID 22314082, 2012). "While CXCR4 favors NB growth and chemotaxis, CXCR7 reduces tumor growth and may be associated to less aggressive stages of the disease." (PMID 22916293, 2012). "OS stem cells were found to express more CXCR4 than normal tumor cells." (PMID 23181114, 2012). "The majority of tumours had moderate CXCR4 expression and accounted for 49% of the cohort." (PMID 22415233, 2012). "CXCR4 is one of the key regulators of tumor invasiveness and metastasis development." (PMID 22359577, 2012). "Interestingly, the volume of NB8×4×7 cell-derived tumors was significantly reduced as compared to that of the NB8×4 group at week 5 (p<0.05), suggesting that CXCR7 significantly affected tumor take of tumors derived from CXCR4-positive NB8×4×7 cells." (PMID 22916293, 2012). "Moreover, we recently reported that stable knockdown of CXCR4 reduced tumour growth in vivo, as measured by imaging of luciferase-transfected cells." (PMID 22322968, 2012). "To further define the roles of CXCR4 in cell migration, we determined whether AMD 3100, an antagonist binding to CXCR4, blocked the tumor cell movement induced by SDF-1α." (PMID 23300882, 2012). "The tumor-derived cells showed a 2- to 7-fold increase in surface CXCR4 expression in flow cytometry results, which indicates the significant retention of radioactivity observed in larger tumors due to 125I-12G5 binding to CXCR4 and not by enhanced permeability and retention." (PMID 22685650, 2012). "The CXCR4/CXCL12 axis has been largely shown to participate in tumor development and progression." (PMID 22916293, 2012). "In addition, we evaluated CXCR4 expression levels on macrophages and tumor cells in the MTLn3 tumors and found that the macrophages in these tumors expressed more CXCR4 than the tumor cells did." (PMID 22314082, 2012). "The effects of HER2-inhibition with trastuzumab and of CXCR4-inhibition with AMD3100 on primary tumor growth, metastatic homing, and receptor expression were evaluated in vitro and in an orthotopic model of metastatic esophageal carcinoma using MRI for imaging." (PMID 23082154, 2012). "This was an intriguing finding because of CXCR4's well-known role in tumor metastasis." (PMID 22359577, 2012). "In contrast to CXCR4, CXCR7 expression was low in undifferentiated tumors, while its expression was stronger in matured tissues and specifically associated to differentiated neural tumor cells." (PMID 22916293, 2012).
tumor (continued). "In fact, similar to Drosophila, chemotaxis is vital for primordial germ cell development in zebrafish and mouse, as Sdf-1/CXCR4 directs their migration and significantly the same chemokine receptor may be involved in metastasis of many tumor cell-types." (PMID 22666326, 2012). "Interestingly, 4 out of 6 metastatic tumours appeared to have a stronger CXCR4 expression as compared to the respective primary tumours (increase of the CXCR4 score, from 2+ to 3+ in cat n." (PMID 22417013, 2012). "CXCR4 expression was observed in 29 out of 31 malignant tissues with a higher CXCR4 score observed in 4 out of 6 metastatic lesions than in the respective primary tumours." (PMID 22417013, 2012). "However, in such environment and in contrast to s.c. conditions, presence of CXCR7 clearly resulted in a delayed tumor take of CXCR4/CXCR7-positive cell-derived tumors, as compared to NB8×4 cell-derived tumors." (PMID 22916293, 2012). "In addition to its critical role in tumor cell growth, survival and angiogenesis in multiple cancers, the CXCR4/CXCL12 pair has been shown to mediate homing and metastatic secondary growth in CXCL12-producing organs, such as liver and bone marrow." (PMID 22916293, 2012). "Collectively, these studies suggest that expression of CXCR4 could provide a selective advantage for interaction with the extracellular matrix and facilitate preinvasive binding of the tumor progenitor cells allowing further tumor dissemination." (PMID 22359577, 2012). "Furthermore, it was shown that imatinib itself also increased CXCR4 expression on CML cells, indicating that treatment itself can prime tumour cells to such a state that they are more susceptible to the protective effects of MSCs." (PMID 22596239, 2012). "Our data indicate that CCR8 and CXCR4 are up-regulated on tumor-infiltrating FoxP3+ T cells." (PMID 22292042, 2012). "There is growing evidence for CXCR4 involvement in the process of tumor progression and metastasis." (PMID 23071744, 2012). "Numerous studies have reported that CXCR4 among all chemokine receptors plays a critical role in tumor invasion and metastasis by interacting with its ligand stromal cell-derived factor-1 (SDF-1 or CXCL12), which is highly expressed in common destination organ sites of metastasis." (PMID 22685650, 2012). "Although lungs metastases were detected in both CXCR4+/+ and CXCR4+/− mice, tumor burden was significantly less in CXCR4+/− mice, Plerixafor treatment further reduced the size and number of lung metastases more effectively in CXCR4+/− mice, preserving the pulmonary architecture." (PMID 22399057, 2012). "CXCR4 is the most frequently expressed chemokine receptor on tumor cells." (PMID 22916293, 2012). "Furthermore, we have demonstrated that hypoxia increases the expression of chemokine (C-X-C motif) receptor 4 (CXCR4) which, in turn, stimulates migration of tumor cells in an in vitro assay." (PMID 21489226, 2011). "The CXCR4 gene can further be transactivated by the activation of HIF-1α, arising from either loss of von-Hippel-Lindau tumor suppressor (VHL) or due to the hypoxic conditions observed frequently in tumor tissues." (PMID 24212934, 2011).
tumor (continued). "However, unmethylated CXCR4 did correlate with the tumor stage (p<0.001), tumor size (p<0.001), histological grade (p<0.001), SBR grade (p<0.001), lymph node status (p = 0.002), metastasis (p = 0.026) and death (p = 0.038)." (PMID 22220212, 2011). "Furthermore, we have shown that this compound inhibits tumor growth in vivo and downmodulates CXCR4 phosphorylation and downstream signaling." (PMID 21915267, 2011). "We have recently proposed that the cure rates for this malignancy might be improved by targeting the SDF-1/CXCR4 pathway, thereby preventing reconstitution of the tumour vasculature following irradiation." (PMID 21587260, 2011). "CXCR4 expression increases tumor cell invasiveness and motility." (PMID 22152016, 2011). "One possibility is that there might be gene expression changes occurring in MTLn3 CXCR4 cells within the tumor microenvironment that provide an advantage in entering the circulation but impair the ability to extravasate or seed lung metastases." (PMID 22152016, 2011). "CXCR4 expression has been shown to be upregulated in MFH tumor cell lines." (PMID 21234386, 2011). "Notably, inhibition of CXCR4 (via both drug and neutralizing antibody) in this tumor model prevented metastatic disease." (PMID 21188169, 2011). "There is therefore a need to determine whether CXCL12 status in EOC depends on its bioavailability and on the CXCR4/CXCR7 ratio in tumor cells, which would support an effect of CXCL12." (PMID 21410972, 2011). "Similarly, blocking of its receptor, CXCR4, resulted in reduced migration of MCs further, strengthening the notion that a CXCL12/CXCR4 axis plays an active role in MC recruitment to the tumor site." (PMID 21949886, 2011). "CXCR4 expression is induced under hypoxic stress via activation of the HIF pathway in a number of cell types including B lymphocytes, tumour associated monocytes and endothelial cells, microglia, multipotent stem cells, stromal cells, cardiac monocytes and fibroblasts." (PMID 21521526, 2011). "The MSP technique was tested with DNA from the tumor cell lines to confirm if this DNA region could be used to analyze the CXCR4 methylation pattern in primary tumors." (PMID 22220212, 2011). "When a CRC cell is turned metastatic, CXCR4 may be an important factor for the homing of such a tumor cell to its favourite organ destination, the liver." (PMID 21349176, 2011). "Like CXCR4, CXCR7 has also been implicated in tumor metastasis." (PMID 21672222, 2011). "Benign tissue adjacent to tumor lesions exhibited weak cytoplasmic CXCR4 staining." (PMID 22295222, 2011). "Given the role of hypoxia in T cell activation, and also specifically in Treg, we hypothesised that Treg recruitment is dependent on both CXCL12 production by tumour cells and hypoxia-induced CXCR4 expression in Treg." (PMID 21521526, 2011). "CXCR4 expressed by tumour cells contributes to their migration into the premetastatic niche." (PMID 21647363, 2011). "A recent study demonstrated that CXCL12/CXCR4 interactions may also promote early extravasation of liver metastatic epithelial tumor cells which determines a critical step in formation of organ-specific metastases." (PMID 21349176, 2011). "Because CXCR4 is known to mediate proliferation, invasion and metastasis of tumor cells, we postulated that plumbagin may modulate the expression of CXCR4 and inhibit tumor cell invasion." (PMID 21880153, 2011). "CXCL12/CXCR4 signaling has been reported to stimulate growth of several tumors including breast, with carcinoma-associated fibroblasts (CAFs) being an important source of CXCL12 in the tumor microenvironment." (PMID 22152016, 2011). "The importance of the CXCL12/CXCR4 axis in tumor progression and metastasis has been emphasized." (PMID 21349176, 2011). "That group speculated that cytoplasmic CXCR4 staining could be indicative of “active CXCR4 functioning,” as if the cancer cells are ready to leave the primary tumor." (PMID 22295222, 2011).
tumor (continued). "Moreover, CXCL12 is expressed in a large number of tumors and injured tissues, and the corresponding activation of its receptor, CXCR4, promotes angiogenesis and metastasis of tumor cells." (PMID 21949886, 2011). "The absence of CXCR4 methylation was associated with the tumor stage, size, histological grade, lymph node status, ESR1 methylation and CXCL12 methylation, metastasis and patient death." (PMID 22220212, 2011). "A higher frequency of CD8+CXCR4+ T cells in the peripheral blood of HR patients may facilitate infiltration of T cells into the tumor site." (PMID 21978632, 2011). "The activity of CXCR4-directed agents has already been shown in animal tumor models and might be of particular interest in rapidly progressing tumors." (PMID 20819239, 2010). "The possibility that CXCR4-tropic HIV might inhibit tumor-promoting macrophages and that CXCR4 may differ between mononuclear and breast cells should be considered." (PMID 21179547, 2010). "The expression of CXCR4 in tumor thrombus tissue was higher than that in HCC tissue." (PMID 21110890, 2010). "However, a different study shows that CXCR4 expression was inversely related to tumor grade and patient outcome." (PMID 20049170, 2010). "The regulation of CXCR4 surface expression by 5T4 molecules is a novel means to control responses to the chemokine CXCL12 for example during embryogenesis but can also be selected to advantage the spread of a 5T4 positive tumor from its primary site." (PMID 20376365, 2010). "A role for the SDF1α/CXCR4 signaling pathway in the development or maintenance of the GBM neovasculature is suggested by a report that demonstrated that the administration of a CXCR4 antagonist to an orthotopic xenograft mouse model of GBM inhibited tumor growth." (PMID 20379377, 2010). "Only 17% of the tumour samples showed a mostly faint CXCR4 immunoreactivity." (PMID 20386750, 2010). "Recently, new evidence indicated that hypoxia may affect the tumor migration process by altering the expression of CXCR4 via activation of HIF-1α." (PMID 20953377, 2010). "EPCs are mobilized from the bone marrow by the cytokine stromal-derived factor-1α (SDF-1α) that is expressed by angiogenic vessels in GBM, SDF1α binds to the G protein-coupled chemokine 4 receptor (CXCR4) expressed on circulating EPCs and also on tumor vessels." (PMID 20379377, 2010). "The increased expression of CXCR4 in endothelial cells observed in our tumour collective might be part of an integrated hypoxic response of the growing tumour that allows for the generation of new blood vessels." (PMID 20386750, 2010). "When oxygen is scarce like in rapidly growing tumours, HIF1α enhances the expression CXCR4." (PMID 20386750, 2010). "The immunoreactivity of CXCR4 was observed in the cytoplasm and/or nucleus of tumor cells." (PMID 20181250, 2010). "TGFβ signalling might be another mechanism involved in tumor dormancy abrogation as SDF-1α/CXCR4 inhibition was insufficient to counteract AT-MSC mediated effect." (PMID 20509882, 2010). "With H. pylori being a potent inducer of TNF-α, whether TNF-α, a tumor promoter, is involved in the induction of CXCR4 expression by H. pylori was also under research in this study." (PMID 20699000, 2010). "When evaluating CXCR4 immunoreactivity in tumour cells, a low expression rate was observed." (PMID 20386750, 2010). "Indeed, in hematological malignancies, tumor cells use CXCR4 for dissemination and progression of the disease, because interactions of CXCR4 with its ligand are critical for hematopoietic cells trafficking and homing to lymphatic tissues." (PMID 20049170, 2010). "Differences in CXCR4 expression in tumor thrombus tissue and tumor tissue." (PMID 21110890, 2010). "Interestingly, CXCR4 expression within a tumor increases, through HIF-1α, as the oxygen concentration decreases; this action enhances the metastatic potential of the tumor cells." (PMID 20502531, 2010).